IL1B (interleukin 1 beta)
Diseases named in the same sentence as IL1B in open-access papers (continued):
Sharing a sentence is not in itself a finding about the gene and the disease.
peritonitis (continued). "In contrast, there was a remarkable decrease in leukocytes, neutrophils, and the expression of IL-6, IL-1β, and TNF-α in PMB-SA combination groups, indicating the attenuation of the inflammatory response in E. coli-induced peritonitis after PMB-SA combination therapy." (PMID 38258081, 2024). "To determine, why VEC-αC did not block neutrophil recruitment in the peritonitis model, we first repeated these experiments, this time after 3 h i.p. stimulation with 50 ng IL-1β." (PMID 38914623, 2024). "To further test the effect of BI6727 in vivo, we also used an MSU-induced peritonitis model, in which IL-1β levels were completely dependent on NLRP3 activation and the increased IL-1β levels upon MSU treatment led to neutrophil infiltration into the peritoneal cavity." (PMID 37698938, 2023). "In a model of zymosan-induced peritonitis, mice lacking Mcu in the myeloid cells, the Mcu(M)−/− mice, exhibited significantly worse clinical scores, and increased levels of IL-1β and tumor necrosis factor (TNF) in the peritoneal cavity." (PMID 37277641, 2023). "Although we have not assayed changes in IL-18 during peritonitis, our analysis of IL-1β production suggests the rapid activation of the NLRP3 inflammasome system following SES challenge." (PMID 37272871, 2023). "Finally, in Kunming mice with peritonitis, NLRP3 and IL-1β expression in the peritoneum were evaluated." (PMID 36077562, 2022). "In air pouch inflammation and peritonitis mouse models, POVPC injection resulted in the production of caspase-1 (p10), IL-1β, and IL-18 in wild-type mice but not in NLRP3-deficient mice." (PMID 33534121, 2021). "Mmp9, Rgs2 and Zfp36l2 were downregulated in both IL-1β-induced conditions, while Lyz2 and Lst1 were downregulated in IL-1β-induced pneumonitis but not peritonitis." (PMID 34001893, 2021). "KA inhibits a series of index in LPS-induced peritonitis in mice, such as TNF-α, IL-33, and IL-1β." (PMID 34884814, 2021). "Moreover, acetate also suppressed the secretion of IL-6 and TNF-α in serum and IL-1β in serum and PLF during LPS-induced peritonitis." (PMID 31337751, 2019). "In an in vivo experiment, TRIM31-deficient mice exhibited higher concentrations of IL-1β in the serum, but not of TNF-α or IL-6 in an LPS-induced peritonitis model." (PMID 29868015, 2018). "Further investigation of carrageenan-induced peritonitis model revealed that nerolidol decreased the levels of polymorphonuclear cells and tumor necrosis factor (TNF-α) in peritoneal lavage as well as interleukin 1 beta (IL-1b) in LPS-stimulated, peritoneal macrophages." (PMID 27136520, 2016). "Uricase treatment in mice, unlike experiments with allopurinol, failed to impact IL1β levels produced in crystal-induced peritonitis." (PMID 25800347, 2015). "Pro-IL-1β processing and subsequent release of mature IL-1β (mIL-1β) rather than its production were found to be increased in peritonitis pMφ, suggesting increased caspase-1 activity." (PMID 22481867, 2012). "Firstly, they compared eryptosis levels and systemic inflammatory markers (such as CRP, IL-6, and IL-1β) in 31 PD patients with acute peritonitis and 34 PD patients with no history of systemic inflammation or peritonitis in the past three months, representing the control group." (PMID 40643488, 2025). "The MSU-induced peritonitis model was used to investigate the regulatory role of USP13 in the activation of the NLRP3 inflammasome in vivo, which is a well-established NLRP3-dependent acute inflammatory model characterized by IL-1β secretion and massive neutrophil influx into the peritoneal cavity." (PMID 41004574, 2025). "In addition, the concentration of pro-inflammatory cytokines TNF-α, IL-6, IL-1β, KC (CXCL1) and MIP-2 (CXCL2) within the peritoneal lavage also demonstrated that SEMA7A holds protective potential during peritonitis." (PMID 38094294, 2023). "No genes exclusively downregulated in IL-1β-induced peritonitis passed the threshold." (PMID 34001893, 2021).
peritonitis (continued). "Furthermore, F240B exerted in vivo anti-inflammatory activity by reducing the intraperitoneal influx of neutrophils and the levels of IL-1β, active caspase-1, IL-6 and monocyte chemoattractant protein-1 (MCP-1) in lavage fluids in a mouse model of uric acid crystal-induced peritonitis." (PMID 33424855, 2020). "Indeed, intraperitoneal administration of dead endothelial cell-derived particles can induce peritonitis in mice, dependent on IL-1α but not IL-1β." (PMID 26549942, 2015). "In the human NLRP3 129S6 mice in a peritonitis model, we show that BAL-0598 dose dependently blocks IL-1β release but not IL-6." (PMID 40892070, 2025). "Moreover, peritoneal MØs isolated from patients under CAPD during peritonitis episodes exhibit increased proinflammatory cytokines expressions, such as IL-1β and tumoral necrosis factor (TNF)-α, compared to macrophages from CAPD patients without peritonitis." (PMID 36982834, 2023). "However, DEXA reduced the pro-inflammatory cytokines (IL-1β and TNF-α) but did not increase IL-10 levels in peritoneal fluid of mice with peritonitis." (PMID 21799673, 2011).
malaria (130 papers, 2005 to 2026). Malaria is a serious and sometimes fatal disease caused by a parasite that commonly infects a certain type of mosquito which feeds on humans. "It has been observed that clinical or severe malaria is associated with increased levels of pro-inflammatory cytokines, including IL-1β, IL-6, IL-8, IL-10, IL-12, IL-13, IL-31, IL-33, and TNF-α." (PMID 39204168, 2024). "Point mutations at position 31 and 511 in the promoter regions, where there is a change to cytosine and adenine, respectively, increase the risk of severe malaria due to reducing the production of circulating IL-1β." (PMID 38404582, 2024). "IL-1β is a pro-inflammatory cytokine that is implicated in the first line of defence against pathogens, including the hepatic and erythrocytic stages of malaria parasites." (PMID 33593344, 2021). "The second genetic variant in immune genes associated with malaria protection in this study was the IL-1β rs1143634 SNP." (PMID 33593344, 2021). "Cyclic paroxysms and high fever are hallmarks of malaria and are associated with high levels of IL-1β, one of the pyrogenic cytokines." (PMID 34456927, 2021). "In humans, many studies show a significant increase of proinflammatory cytokines such as IL-1β and IL-18 and its association with fever episodes and severity of disease in symptomatic malaria patients." (PMID 29495555, 2018). "Cyclic paroxysm and high fever are hallmarks of malaria and are associated with high levels of pyrogenic cytokines, including IL-1β." (PMID 24453977, 2014). "This indicates that protection against blood-stage malaria is associated with low production of IL-1β, TNFα, IL-6 and a high biphasic production IFNγ by the liver." (PMID 25408684, 2014). "In conclusion, IL-1β levels in cord blood predict IL-1β levels, parasite density, and severe malaria risk throughout infancy." (PMID 24130857, 2013). "IL-1β levels at birth are related to future IL-1β levels as well as the risk of severe malaria in early life." (PMID 24130857, 2013). "We report for the first time that high levels of IL-1β in cord blood persist, and are associated with both improved control of parasite density and with decreased risk of severe malaria during infancy." (PMID 24130857, 2013). "In Cox regression analyses, high levels of IL-1β at birth decreased the risk of first severe malaria episode (hazard ratio (95% CI, P-value) of 0.60 (0.39 - 0.92, P = 0.02))." (PMID 24130857, 2013). "Our results show for the first time that higher levels of the pro-inflammatory cytokine IL-1β at birth are significantly associated with improved control of parasite density and with decreased risk of severe malaria during early life." (PMID 24130857, 2013). "Complementary studies in IL1B gene and IL-1β levels are important to help understand how this gene influences malaria susceptibility and severity." (PMID 23217179, 2012). "In another study conducted in Gambia, significant associations between variations in IL1A +4845G>T (rs17561) and IL1B +3954C>T (rs1143634) were associated with symptomatic malaria." (PMID 23316245, 2012). "These receptors initiate signalling cascades that activate nuclear factor kappa B (NF‐κB), leading to increased production of pro‐inflammatory cytokines such as TNF‐α, interferon‐gamma (IFN‐γ), IL‐1β and IL‐6, all of which are implicated in the pathogenesis of malaria." (PMID 40847608, 2025). "Elevated levels of TNF-α, IL-1β, and IL-6 are commonly associated with severe malaria." (PMID 38694310, 2024). "Additionally, a study in The Gambia demonstrated significant associations between variation at IL-1β +3953 position (rs1143634 C/T) and susceptibility to clinical malaria." (PMID 38404582, 2024). "High IL-1β was highly associated with disease severity and death during malaria." (PMID 36782344, 2023). "In cerebral malaria, increased IL-1β production was shown to associate with malaria pathogenesis." (PMID 36309676, 2022).
malaria (continued). "A high incidence of the IL1A gene polymorphism (−4845G > T), which leads to an increased IL-1α production, is described in Vietnamese patients with severe malaria, and high serum levels of IL-1β are also associated with severe disease in individuals from West Africa24,25." (PMID 31110285, 2019). "Driving the hypochromic morphology observed with both IC and CHQ-treated animals is a synchronous release of parasite pyrogens such as tumour necrosis factor-α (TNF-α) and interleukin-1β (IL-1β) that are also associated with anaemia, various pathologies and death from malaria." (PMID 27098750, 2016). "Our data suggest a graded activation of pathways downstream of the pro-inflammatory cytokines IFNγ, TNF, and IL-1β that is associated with prior malaria-exposure, with naïve individuals having the greatest activation and malaria-experienced asymptomatic individuals having the least." (PMID 27506615, 2016). "Severe malaria was also associated with higher levels of IL-1β (p = 0.008), IL-2 (p = 0.001), IL-4 (p = 0.041), IL-12p70 (p = 0.010), IL-13 (p = 0.004), IFN-γ (p = 0.041), TNF (p = 0.049), IFN-γ/IL-10 (p = 0.016), TNF/IL-10 (p = 0.016) and (TNF + IFN-γ)/IL-10 (p = 0.001) than mild malaria." (PMID 26466783, 2015). "Analysis of SNPs in the IL22 gene found several weak associations with severe malaria in Gambian children but no clear cut effect while a SNP in IL1A (encoding interleukin1α) and another in IL1B (encoding interleukin-1β) showed a marginal association with susceptibility to malaria." (PMID 24312262, 2013). "Our finding that high levels of cord blood IL-1β reduce the risk of severe malaria is also consistent with a study showing that IL-1β promoter haplotype -31C/-511A is associated with decreased production of IL-1 and increased risk of severe malarial anaemia in Kenyan children." (PMID 24130857, 2013). "To investigate a potential role for UA in malaria pathogenesis, we first measured the levels of ten cytokines (IL-6, IL-10, MCP-1, sTNFRII, IL-8, IP-10, TNFα, IFNγ, GM-CSF and IL-1β) that other studies have implicated in the development of severe malaria in humans." (PMID 23071567, 2012). "The rapid induction of IL-1β might help control invading malaria parasites through the induction of an acute inflammatory response as part of the first line of defense; however, the overproduction of IL-1β might cause severe pathogenic effects." (PMID 23316245, 2012). "In a gene-based association study with 18 candidate genes for malaria susceptibility using 33 SNPs as genetic markers, this study demonstrated that IL1B, IL4R, IL12RB1 and TNF genes were associated with susceptibility to P. vivax malaria in a population of Pará state, Brazil." (PMID 23217179, 2012). "Genotype and allele frequencies of IL1B -31C/T polymorphism in Thai malaria patients." (PMID 16098232, 2005). "Future studies with sufficient sample sizes should assess whether elevated IL-1β levels at birth reduce risk of all severe malaria symptoms equally or only of specific syndromes, and also whether a threshold level of IL-1β is required for the protective effect." (PMID 24130857, 2013). "Finally, we analysed the influence of cord blood TNF-α and IL-1β levels on severe malaria risk." (PMID 24130857, 2013). "The concurrent increase in CCL3 and IL-1β underscores the need to further investigate whether these immune responses confer enhanced parasite control, increased risk of immunopathology, or represent a unique adaptation of chimpanzees to chronic malaria exposure." (PMID 41279035, 2025). "On the contrary, the level of IL-1β was significantly lower in the malaria group with a higher level of IL-10." (PMID 40014608, 2025). "IL-1β levels in the malaria mono and typhoid mono groups were significantly compared to the typho-malaria group (p < 0.05)." (PMID 40014608, 2025). "A role of IL-1β in malaria severity has been reported while in the case typhoid fever, the findings are inconsistent." (PMID 40014608, 2025).
malaria (continued). "Previous studies have shown that certain components of FFR can downregulate pro-inflammatory cytokines such as TNF-α and IL-1β, which are involved in the pathogenesis of neuroinflammation during malaria." (PMID 40892845, 2025). "Children with severe malarial anemia had higher plasma levels of TNF‐α (p < .001), IFN‐ɣ (p < .001), IL‐1β (p < .001), IL‐6 (p < .001), GM‐CSF (p < .001), and IL‐10 (p < .001) than those with malaria only, and mild/moderate anemia." (PMID 39240033, 2024). "Preclinical studies targeting IL-1β have demonstrated reduced inflammation and improved survival in severe malaria models." (PMID 38694310, 2024). "Increased levels of IL-1β and TNF, beyond TGF-b and IL-10, are associated with the major severity of malaria." (PMID 38774541, 2024). "In the present study, children with severe malarial anemia had significantly elevated plasma levels of TNF‐α, IFN‐ɣ, IL‐1β, IL‐6, GM‐CSF and IL‐10 than those with uncomplicated malaria, and this is in consonance with earlier findings." (PMID 39240033, 2024). "A proportional increase in TGF-β and TNF-a, IL-10, and IL-1β, predicts a proportional increase in severe forms of malaria, especially in CM patients." (PMID 38404582, 2024). "In malaria, macrophages release IL-1β and TNF-α after recognizing PAMPs such as glycosylphosphatidylinositol and hemozoin." (PMID 38774541, 2024). "In vitro, SMQ was more lytic to macrophages than LMQ, which limited its ability to induce TNF-α and IL-1β and offered lower protection against malaria." (PMID 37913775, 2023). "Studies on IL-1β in the context of malaria are limited and the results are inconsistent; therefore, conclusions on IL-1β in various types of malaria are unclear." (PMID 36309676, 2022). "The results from the meta-analysis revealed that IL-1β levels were higher in patients with severe malaria than in patients with uncomplicated malaria; however, IL-1β levels were similar in patients with uncomplicated malaria and healthy controls." (PMID 36309676, 2022). "Future studies to determine differences in IL-1β levels in malaria in pregnancy are suggested, because pregnant women are a frequently neglected and highly vulnerable population." (PMID 36309676, 2022). "Of the 10 studies that compared IL-1β levels between patients with uncomplicated malaria and healthy controls, 6 provided quantitative data on IL-1β levels in uncomplicated malaria (542 cases) and healthy controls (455 individuals)." (PMID 36309676, 2022). "A qualitative synthesis of the 12 studies revealed that severe malaria had higher IL-1β levels than uncomplicated malaria." (PMID 36309676, 2022). "Of 20 studies included in this study, 10 that compared IL-1β levels between patients with uncomplicated malaria and healthy controls were included for qualitative and quantitative syntheses." (PMID 36309676, 2022). "Of the 20 studies included, 12 that compared IL-1β levels between severe and uncomplicated malaria were included for qualitative and quantitative syntheses." (PMID 36309676, 2022). "A qualitative synthesis of 10 studies providing data on IL-1β levels between patients with uncomplicated malaria and healthy controls revealed that 6 reported higher IL-1β levels in patients with uncomplicated malaria than healthy controls." (PMID 36309676, 2022). "Third, publication bias was caused due to small-study effects in the meta-analysis of MDs between patients with uncomplicated malaria and healthy controls, indicating the need for more studies providing data on IL-1β levels in the meta-analysis." (PMID 36309676, 2022). "The meta-analysis results suggested that IL-1β levels were higher in patients with severe malaria than patients with uncomplicated malaria." (PMID 36309676, 2022). "Based on the limitations of the number of studies included in the meta-analysis and high levels of heterogeneity, further studies are needed to conclude that differences in IL-1β levels can be useful for monitoring malaria severity." (PMID 36309676, 2022).